MYC (MYC proto-oncogene, bHLH transcription factor)
Diseases named in the same sentence as MYC in open-access papers (continued):
Sharing a sentence is not in itself a finding about the gene and the disease.
pancreatic cancer (continued). "Blocking STAT3 axis by PS-Gp130 and MYC peptides inhibits tumor growth and increases tumor infiltration of cytotoxic CD8+ T cells in mouse pancreatic cancer model." (PMID 33491667, 2021). "In previous study, we demonstrated the CD110-Thrombopoitin (TPO) axis promoted pancreatic cancer progression and liver metastasis by activating ERK1/2 and MYC." (PMID 34295827, 2021). "Bioinformatics analyses highlighted a positive correlation between MYC and BPTF in MYC-addicted tumors including BL, as well as prostate, colorectal, and pancreatic cancer." (PMID 33801599, 2021). "Collectively, we demonstrated that eIF4A1 overexpression downregulated E-cadherin expression through the c-MYC/miR-9 axis, which promoted EMT and the metastasis of pancreatic cancer cells in vitro and in vivo." (PMID 34906136, 2021). "Overexpression of eIF4A1 downregulated E-cadherin expression through the c-MYC/miR-9 axis, which promoted EMT and metastasis of pancreatic cancer cells." (PMID 34906136, 2021). "Loss of eIF4A1 and c-MYC decreased the EMT and metastasis capabilities of pancreatic cancer cells, whereas upregulation of eIF4A1 attenuated the inhibition of EMT and metastasis induced by c-MYC downregulation." (PMID 34906136, 2021). "We then determined c-MYC status in the pancreatic cancer tissue specimens by immunohistochemistry and evaluated if MUC16 levels correlate with c-MYC levels." (PMID 26046375, 2015). "We observed elevated expression of PI3K, c-MYC and phosphorylation of ERK in HER2 knockdown cells than control cells, suggesting that HER3/MUC4 mediated hyperproliferation of HER2 low pancreatic cancer cells through the PI3K/ERK/c-Myc pathway." (PMID 26035354, 2015). "Furthermore, TCGA data portal shows that human PDACs exhibit amplifications and mutations in ADAM10, MYC, VIM (vimentin), CD44, CCND1 (CyclinD1) and CTNNB1 (β-catenin), implying the importance of interfering with the signaling associated with these in prevention of pancreatic cancer." (PMID 26440150, 2015). "Our results demonstrate down-regulation of glycolytic genes as well as reduced activation of Akt and mTORC1, which can regulate c-MYC expression, in MUC16 knockdown pancreatic cancer cells." (PMID 26046375, 2015). "In pancreatic cancer cells, pulse of NOTCH1 activation led to increased expression of NOTCH target genes namely HES1 and c-MYC." (PMID 24392017, 2013). "In pancreatic cancer (PC), tiRNA-Val-CAC-2 enhances pancreatic cancer cell migration and invasion by binding to the RNA-binding protein far upstream element-binding protein 1 (FUBP1), increasing its stability, and activating c-MYC transcription." (PMID 41550494, 2026). "The simultaneous increase in MYC and PD-L1 in GEM-resistant pancreatic cancer cells suggests that MYC may influence GEM resistance through regulating glycolysis." (PMID 39990228, 2025). "MYC eRNAs dynamically interact with YEATS2 protein and recruit the YEATS2-containing ATAC complex to the MYC promoter to induce MYC gene transcription in pancreatic cancer." (PMID 40216980, 2025). "It was demonstrated that MYC preferentially triggers transformation of the most immature MSI2+ pancreas cells into multi-lineage pre-cancer cells, which diverge to establish pancreatic cancer subtypes by activating distinct transcriptional programs and large-scale genomic changes." (PMID 41255572, 2025). "However, pancreatic cancer cells typically acquire resistance to BET inhibitors and c-MYC is thought to be responsible for this." (PMID 40100307, 2025). "We hypothesise that partial depletion of MAX is neutral in pancreatic tumours, since MAX also forms repressive homodimers and heterodimers that bind to similar DNA motifs and compete with the gene-activating capacity of the MYC/MAX heterodimers." (PMID 38821858, 2024).
pancreatic cancer (continued). "Notably, glutamine reportedly stabilizes c‐MYC via α‐ketoglutarate to prevent c‐MYC degradation through the ubiquitination–proteosomal pathway, thus weakening the sensitivity of pancreatic cancer cells to paclitaxel." (PMID 39534558, 2024). "We concluded that MYC and the RUVBL1/2 complex bind to each other, explaining their co-occupancy on thousands of promoters and the relevance of RUVBL1 for MYC-mediated gene regulation and growth of pancreatic cancer cells." (PMID 38821858, 2024). "We observed that oncogenic MYC expression renders cells dependent on the activity of the RUVBL1/2 complex and that acute depletion or inhibition of RUVBL1 provokes immune infiltration and eradicates pancreatic tumours in mice." (PMID 38821858, 2024). "To this end, we first quantified MYC and RUVBL1 levels in a panel of pancreatic cancer cells by immunoblotting and observed a strong correlation between the levels of both proteins and between their levels and sensitivity to CB-6644 as estimated in cell growth assays." (PMID 38821858, 2024). "From the dose–response results, we selected two of the most efficient PPRHs for each gene, G4-C and I1-T for MYC-targeting PPRHs and PR-C and PPRH 2 for KRAS-targeting PPRHs; these PPRHs were also the most effective against the pancreatic cancer cell line, AsPc-1." (PMID 39457457, 2024). "In pancreatic cancer, elevated levels of the MUC5AC glycoprotein contribute to the disruption of the E-cadherin and β-catenin junction, followed by the nuclear translocation of β-catenin, which ultimately increases MYC expression levels." (PMID 37443779, 2023). "Importantly, some of these results were obtained with endogenous c-MYC levels, suggesting that c-MYC can participate in tumor progression without being overexpressed and supporting its importance in pancreatic cancer biology." (PMID 33669845, 2021). "On a Kras-mutant background, hyperglycemia may contribute to pancreatic cancer progression via STAT3 phosphorylation and elevated MYC expression." (PMID 32609742, 2020). "Meanwhile, pancreatic cancer stem cells rely on mitochondrial OXPHOS, which may be correlated with the suppression of MYC and the MYC/PGC-1α ratio, so mitochondrial agents and genetic therapy can easily target this phenotype." (PMID 33256814, 2020). "Using the methods outlined in this study, we found that germline deletions of TUSC3 and near MYC were more prevalent among participants without pancreatic cancer." (PMID 32894098, 2020). "MYC reprograms pancreatic cancer metabolism, independent of MAPK signaling and the MAPK effector ERK." (PMID 32609742, 2020). "Moreover, CA125 serves as a prognostic marker for patients with pancreatic cancer, and mechanistic studies found that the KRAS/MYC axis drives the upregulation of MUC16/CA125." (PMID 31662990, 2019). "In addition, we analyzed the expression of the c-MYC, HMGA2 and KRAS mRNAs in the pancreatic cancer samples from the GSE data sets." (PMID 28947981, 2017). "The interaction between endogenous c-MYC and BPTF was validated in MIA PaCa-2 pancreas cancer cells, expressing high levels of both proteins, using the in situ proximity ligation assay (isPLA) and affinity-purified rabbit antibodies recognizing BPTF residues 913–942." (PMID 26729287, 2016). "Furthermore, we analyzed the mRNA level of c-MYC in MUC16-high and MUC16-low human pancreatic cancer tissue specimens." (PMID 26046375, 2015). "The non-stem pancreatic cancer cells under intermittent hypoxia for 72 h significantly increased the expression levels of Oct-4 and c-MYC in comparison to those under normoxia." (PMID 24305593, 2013).
pancreatic cancer (continued). "Here, we observed downregulation of c-MYC and KRAS via let-7a in AsPC1 tumor xenografts following the knockdown of DCLK1 (a similar mechanism was previously demonstrated in pancreatic cancer cells)." (PMID 24040120, 2013). "However, in certain types of tumors, such as pancreatic cancer, knockdown of MYC does not result in tumor cell apoptosis in vitro." (PMID 40732268, 2025). "To test whether activation of MYC target genes and repression of immune genes is a general function of RUVBL1 in pancreatic cancer cells, we treated five further murine PDAC lines with different genetic backgrounds with CB-6644 for 24 hours and analysed gene expression by RNA sequencing." (PMID 38821858, 2024). "Lnc01420 is upregulated in pancreatic cancer and facilitates pancreatic cancer cell proliferation, metastasis and EMT, and lnc01420 can act as a sponge of miR-494-3p to relieve the inhibition of MYC expression and promotes KRAS gene transcription through the lnc01420/miR-494-3p/MYC regulatory axis." (PMID 35819532, 2022). "FBXW7 dramatically suppresses glucose metabolism and reduces the 18F-FDG uptake of pancreatic cancer cells through regulating the expression of thioredoxin binding protein (TXNIP) in a c-MYC-dependent manner, whose regulatory mode can be summarized into the FBXW7/c-MYC/TXNIP axis." (PMID 35515121, 2022). "In summary, the tetracycline-controlled expression models for pancreatic cancer have been instrumental for the identification of cellular processes and molecular pathways by which a subset of cancer cells can escape a targeted ablation of KRAS and its downstream effector c-MYC." (PMID 34491463, 2021). "Paradoxical dimerization of c-RAF and alternate compensatory signaling cascades, such as possible signaling through other RAF isoforms, could explain the maintenance of MYC expression in GW5074 treated murine PAN 02 tumors and failure to improve survival of pancreatic tumor bearing mice." (PMID 34947972, 2021). "The alteration of c-MYC alone is not sufficient for the development of pancreatic tumors." (PMID 28383487, 2017). "However, MYC proteins themselves may modulate resistance to JQ1, which has been recently described for pancreatic cancer cells up-regulating c-MYC in response to JQ1." (PMID 27769070, 2016). "The MYC amplified cases did not have a higher mutation burden or association with other hallmark mutations of PDA; however, amplification was significantly over-represented in the adenosquamous subtype of pancreatic carcinoma." (PMID 25855536, 2015). "Furthermore, the mRNA and protein levels of Oct-4 and c-MYC were significantly increased in CD133+ pancreatic cancer stem-like cells compared to CD133- non-stem pancreatic cancer cells." (PMID 24305593, 2013). "This novel eRNA-protein interaction might be significant in unraveling the functional consequences of MYC enhancer-driven RNAs in regulating MYC gene expression in PDAC, which can also pave the way for targeting MYC gene regulation preventing worse prognosis of pancreatic cancer patients." (PMID 40216980, 2025). "However, FURIN positively acted with MYC in pancreatic cancer, but not in the mixed cancer dataset." (PMID 33796097, 2021). "Differentiated pancreatic tumor cells highly express c-MYC and, hence, exhibit low levels of PGC-1α; however, in cancer stem cells (CSCs), c-MYC is not highly expressed and PGC-1α levels are amplified." (PMID 32354000, 2020).
pancreatic cancer (continued). "By activating MAPK dependent signaling pathway, KRAS leads to MYC up-regulation and transcription of nonoxidative pentose phosphate pathway (PPP) gene RPIA, thus promoting nucleotide biosynthesis and accelerating the development of pancreatic cancer." (PMID 38598912, 2024).
multiple myeloma (392 papers, 2007 to 2026). "In this context, 2 key myeloma markers, MYC and DKK1, as well as many other cancer-associated genes, including ADM, HDGF, IL15, HGF, STMN1, CDKN1B and CD82, were potentially regulated by the predicted ligands." (PMID 41056512, 2025). "Approximately 50% of PBL cases exhibit MYC alterations; however, its concomitant association with plasma cell myeloma and plasmablastic myeloma reduces its diagnostic utility." (PMID 39944461, 2025). "Here the authors show that sporadic MYC activation in Vk*MYC mice is sufficient to induce tumors with a variety of secondary mutations that mirror the genetic heterogeneity of human myeloma." (PMID 38714690, 2024). "Inactivation of OTUD6B almost completely eliminates the growth of multiple myeloma (MM) in vivo through cell cycle arrest at the G1/S checkpoint, which is consistent with the associated loss of MYC expression." (PMID 38880876, 2024). "On the other hand, MYC amplifications at 8q24.21 locus are present from MGUS to full-blown myeloma in about 15% of patients and associate with poor prognosis." (PMID 39482742, 2024). "A recent study found that targeting fatty acid binding proteins (FABPs), including FABP5, in MM reduced MYC signalling and induced apoptosis of myeloma cells, highlighting the association of aberrant lipid metabolism with MM." (PMID 37568580, 2023). "We and others showed that super-enhancers were associated to key genes contributing to myeloma pathogenesis, such as MYC, IRF4, CCND1, NSD2 and MAF39,66." (PMID 35198065, 2022). "The loss of active chromatin at super-enhancers critical for multiple myeloma, including the super-enhancer controlling the proto-oncogene c-MYC, reduces metabolic activity and cancer cell growth." (PMID 36846090, 2022). "BRD7 as well as ARID2 were also associated with MYC and MYC target gene expression and with poorer prognosis in multiple myeloma." (PMID 35323214, 2022). "A mutated version of the MYC IRES prevalent in multiple myeloma (MM) binds tightly to hnRNP K, thus promoting increased aberrant expression of MYC." (PMID 36452487, 2022). "MYC upregulation is associated with multidrug refractory disease in patients with multiple myeloma (MM)." (PMID 34864816, 2021). "Multiple myeloma (MM), in particular, is a plasma cell malignancy strictly associated with MYC deregulation, suggesting that therapeutic strategies against it would be beneficial in treating this disease." (PMID 35582389, 2021). "Inhibition of EP300/CBP causes acute repression of IRF4 and MYC in myeloma cells, further indicating that MM cells are strongly dependent on these two key transcription factors." (PMID 34834536, 2021). "As expected, positively enriched terms were associated with MYC transcriptional regulation, myeloma pathogenesis, and general cancer biology." (PMID 34732728, 2021). "Plasmacytoma Variant Translocation 1 (PVT1), a lncRNA, is located adjacent to the gene MYC, which has been linked to multiple myeloma (MM)." (PMID 32992461, 2020). "MYC activation is associated with hyperdiploid MM and shorter survival, and also plays a causal role in the progression of monoclonal gammopathy to multiple myeloma." (PMID 31956364, 2020). "This was determined with a CRISPR-Cas9 engineered multiple myeloma cell line which had one allele of c-MYC tagged with GFP." (PMID 32759815, 2020). "In myeloma, MYC structural variants are spread across at least two broad regions and serve to amplify or transpose large enhancers to drive MYC expression." (PMID 31231360, 2019). "The newly established super-enhancer profoundly increases the expression of MYC, causing an aggressive disease phenotype in myeloma patients." (PMID 31311566, 2019). "MYC has recently been shown to be activated in 67% of myeloma samples and is associated with hyperdiploidy." (PMID 30696815, 2019).
multiple myeloma (continued). "Secondly, although both myeloma cell lines and primary cells expressed high amounts of MYC, there are differences in the underlying mechanisms behind the expression." (PMID 26087190, 2015). "Unsurprisingly, these regions are associated with genes having a role in multiple myeloma biology, including c-MYC." (PMID 26569311, 2015). "Multiple myeloma cells express high levels of MYC, associated with downregulation of NCoR2." (PMID 37450923, 2024). "High c-MYC gene levels in myeloma cells are associated with LEN resistance." (PMID 38004369, 2023). "To summarize, we define how proteasome inhibition alters the chromatin-associated landscape in multiple myeloma by stabilizing repressor complexes at super-enhancers, including the one controlling c-MYC, and at promoters of genes driving proliferation and metabolism." (PMID 36846090, 2022). "Moreover, the dual blockade of RSK2 and AKT exerted robust molecular effects on critical gene sets associated with myeloma pathophysiologies, such as those with MYC, mTOR, STK33, ribosomal biogenesis, or cell-extrinsic stimuli of soluble factors, in HMCLs." (PMID 35328342, 2022). "The realization that Vκ*MYC-dependent myeloma causes changes in immune regulation in mice comparable to changes seen in patients with myeloma laid the foundation for mechanistic studies describing role of specific pathways of immunity to Vκ*MYC-driven tumor development." (PMID 34149703, 2021). "Additionally, in many other cancers including T cell leukemia, chronic myeloid leukemia and multiple myeloma, MYC expression was linked to the super-enhancers acquired in tumor cells." (PMID 33859327, 2021). "Loss of FAM46C in myeloma promotes cell survival inducing MYC expression." (PMID 30337605, 2018). "The progression of MGUS to myeloma is associated with several-fold increase in MYC RNA expression." (PMID 24252328, 2013). "Thus, low CD302 expression may be closely associated with abnormal activation of the MYC pathway and the development of multiple myeloma." (PMID 41323386, 2025). "We suspect that the high level of ISR-GCN2 activity in Vκ*MYC mice with early disease reflects an adaptive mechanism employed by myeloma cells to cope with cellular stress associated with transformation, but whether this is directly mediated by MYC has yet to be determined." (PMID 34732728, 2021). "This is particularly relevant given that the SUMO cycle is dysregulated in multiple myeloma, has been associated with an adverse outcome in cancer patients, and inhibition of a SUMOylation-dependent transcriptional program induces death of MYC-over-expressing cancer cells." (PMID 27513743, 2016). "The transcription factor MYC is a key regulator of cellular proliferation and metabolism and is frequently dysregulated in malignancies such as multiple myeloma (MM)." (PMID 41965876, 2026). "Examples include TRA::MTCP1 for T-PLL, TYK2 rearrangement for T-cell lymphomas; CCND1 and CCND2 rearrangement with IGK and IGL in mantle cell lymphoma; MYC rearrangements and hyperdiploidy in multiple myeloma." (PMID 40361363, 2025). "Treatment of multiple myeloma cell lines with DC-34 revealed suppression of c-MYC transcription with minimal perturbation of other G4-bearing oncogenes, such as KRAS and BCL-240." (PMID 41366211, 2025). "Following intravenous injection of Vk*MYC myeloma cells, all wild-type (WT) littermate recipient mice developed MM as measured by the presence of M-protein on serum protein electrophoresis (SPEP), confirming successful tumor engraftment." (PMID 41373634, 2025). "This suggests a distinct mechanism of action for TAZ in blood cancers, and indeed, it was shown that TAZ exerts its anti-cancer activity via down-regulation of MYC and induction of miR-224 in multiple myeloma." (PMID 40440076, 2025). "Anlotinib has been shown to directly target c-Myc in multiple myeloma, and reverse resistance through targeting the c-MET/MYC/AXL axis in NSCLC." (PMID 40316534, 2025).